BRCA1 (BRCA1 DNA repair associated)
Diseases named in the same sentence as BRCA1 in open-access papers (continued):
Sharing a sentence is not in itself a finding about the gene and the disease.
breast cancer (continued). "As our findings indicate that patients with non‐BRCA1/2 PVs had low TC scores, the score is not entirely comprehensive in its ability to be used as a sole designator for further genetic testing for breast cancer development." (PMID 41568159, 2026). "We identified the BRCA1 pseudogene (BRCA1P1), a fusion pseudogene derived from the BRCA1 tumor suppressor and RPLP1 ribosomal protein genes, as an immunoregulatory RNA in breast cancer." (PMID 42081726, 2026). "Germline BRCA1 and BRCA2 mutations enable targeted therapies in human epidermal growth factor receptor 2 (HER2)-negative advanced breast cancer (ABC)." (PMID 41965791, 2026). "Following doxorubicin treatment of breast cancer cells, PRMT5 induces nuclear translocation of the RNA demethylase ALKBH5, which removes m6A methylation from BRCA1 mRNA, stabilizing the transcript and enhancing DNA repair capacity to ultimately attenuate doxorubicin efficacy." (PMID 40919714, 2025). "Similarly, of the 913 patients who underwent GT in Post, 623 breast cancer patients were included, excluding ovarian cancer patients and those who underwent RRSO at or below the recommended age (35 years for BRCA1 and 40 years for BRCA2)." (PMID 40399479, 2025). "HRD extends beyond BRCA1/BRCA2 mutations to include non-BRCA genes (RAD51C/RAD51D, BRIP1, BARD1, ATM, PALB2), broadening actionable targets across ovarian and breast cancer subtypes, including HER2-positive (30–40%) and luminal subtypes (15–25%)." (PMID 40864792, 2025). "BRCA1/2, ATM, CHEK2, and PALB2 PV carriers do not have breast cancer OR ≥2.0 with many established risk factors." (PMID 40298171, 2025). "Thus, the prevalence of BRCA1 and BRCA2 VUS carriers among Brunei breast cancer patients was 8.3% and 25.8%, respectively." (PMID 40531958, 2025). "In a study using breast cancer cell lines, the combination of trabectedin and olaparib induces an artificial synthetic lethality effect, regardless of BRCA1 status." (PMID 40243501, 2025). "In the breast cancer samples of the MSK-CHORD cohort, we found only 8 FGFR3-mutant samples, none of which harbored BRCA1/2 mutations." (PMID 40460005, 2025). "Consistent with this, we observed that functions were not shared among subtypes, and only in the BRCA1 breast cancer subtype, immune biological functions were redundant among genes." (PMID 40647506, 2025). "Approximately 72% of BRCA1 carriers and 22–34% of BRCA2 and PALB2 carriers diagnosed with breast cancer present with triple-negative breast cancer (TNBC) a particularly aggressive biologic subtype that almost always necessitates chemotherapy even if tumors are small at diagnosis." (PMID 40275390, 2025). "Moreover, HBOC increases the likelihood of multifocal and synchronous breast cancers; in a cohort of BRCA carriers, MF/MC disease occurred in 25% overall and was more than twice as frequent in BRCA2 than in BRCA1." (PMID 41209903, 2025). "We compared the distributions of breast cancer risk factors including ANM, AAM, the interval between ANM and AAM, menstrual cycle length, height and BMI in a cohort of BRCA1 and BRCA2 PV carriers, and non-carriers, from a large national study." (PMID 40399999, 2025). "As in breast cancer, ovarian cancer breakpoint distributions clustered around NPC breakpoints, even without a hereditary BRCA1 or BRCA2 gene mutation driver." (PMID 39885374, 2025). "BARD1 carriers favor the development of high-grade invasion breast cancer, the same as BRCA1 carriers (p-value = 0.204), while BRCA2 carriers and non-carriers develops less aggressive tumors (p-values = 0.004 and <0.001 respectively)." (PMID 40805222, 2025). "In the US, it is estimated that only 10% of those without a history of breast cancer who are BRCA1 or BRCA2 carriers have been identified and these unaffected women account for approximately 220,000 of the over 348,000 variant carriers." (PMID 40862808, 2025).
breast cancer (continued). "This has led to recommendations from multiple studies, including the American Society of Breast Surgeons, for broader genetic testing, encompassing BRCA1/2, PALB2, and other appropriate genes based on the clinical picture, for all patients with a history of breast cancer." (PMID 40941615, 2025). "It is appropriate that the recently released American Society of Clinical Oncology/Surgical Society of Oncology genetic testing guidelines endorse germline testing for BRCA1 and BRCA2 in all newly diagnosed women with breast cancer who are younger than age of 65 years." (PMID 40952741, 2025). "The peptides upregulate suppressors NR3C1, BRCA1, BRCA2, SFN, and RB1, which may initiate apoptosis processes and growth regulation in breast cancer cells, potentially preventing tumor progression." (PMID 40043049, 2025). "We observed a similar effect by pharmacological GSK3B inhibition using SB216763 on PARPi sensitization in murine breast cancer cell 4T1 regardless of BRCA1 status and BRCA1-proficient human breast cancer cells MCF7." (PMID 41243969, 2025). "This protein acts downstream of the enzyme poly-ADP ribose polymerase, which is a common target of breast cancer therapies due to the synthetic lethality of the treatment in the absence of BRCA1/2." (PMID 40429877, 2025). "BRCA1 promoter hypermethylation is an epigenetic change that silences expression of BRCA1 protein and is reported to drive an HRD phenotype in ovarian and breast cancers but is not captured through DNA mutation calling." (PMID 41248118, 2025). "A family history of breast cancer was reported in six cases (26.09%), though BRCA1/2 (breast cancer 1/2) genetic testing was not routinely performed." (PMID 40248551, 2025). "Among TNBC stage I-III breast cancers with early (N = 134) and late (N = 66) recurrence, the most frequent alteration was PIK3CA (20.2% vs 33.3%), followed by BRCA1/2 (6.0% vs 9.1%), PD-L1 amplification (2.2% vs 3.0%), PALB2 (1.5% vs 0%), and ESR1 (0% vs 1.5%)." (PMID 40421962, 2025). "We used an isogenic pair of human breast cancer cell lines MDA-MB-436, which are inherently BRCA1 deficient, reconstituted with or without wtBRCA1." (PMID 41243969, 2025). "A previous report had shown that the Wnt3a/GSK3β/Slug/Snail axis controlled the epithelial–mesenchymal transition (EMT) in association with Zeb1/2, vimentin, and fibronectin while coordinately repressing BRCA1 and BRCA2 expression in breast cancer cells exposed to DNA damage." (PMID 40001953, 2025). "More common than false negative test results are misapprehensions that a negative BRCA1 or BRCA2 test result in a woman at risk of familial breast and ovarian cancer means the patient will not develop a breast cancer." (PMID 40473778, 2025). "When β1 is large, β2>12β1, as is observed for BRCA1, BRCA2 and PALB2 for breast cancer." (PMID 39749474, 2025). "A previous study in Qatar evaluated the impact of BRCA1 and BRCA2 pathogenic mutations on breast cancer aggressiveness in carriers versus non-carriers, involving 82 women diagnosed with breast cancer at the age of 50 or younger." (PMID 41463058, 2025). "The results showed that BRCA1 carriers with breast cancer who underwent CRRM were less likely to develop CBC (p < 0.0001), and women who developed CBC were twice as likely to die of breast cancer (HR 2.22; 95% CI 1.49–3.32; p < 0.0001)." (PMID 39858629, 2025).
breast cancer (continued). "Although the biological differences between BRCA1- and BRCA2-associated breast cancers have been extensively studied, there is a lack of studies investigating how different treatment regimens influence QoL outcomes in this population." (PMID 40422528, 2025). "BRCA1 carriers who underwent BO before age 45 years and received estrogen-alone HRT showed a nonsignificant yet numerical reduction of breast cancer risk (HR 0.47, 95% CI 0.20–1.15, P = 0.1), vis-à-vis their counterparts not taking HRT137." (PMID 39522613, 2025). "Such analysis by bioinformatics showed that there was a correlation between PARP1 and BRCA1/2, and at the same time, with ESR1 in the HER2 subgroup; those breast cancer patients can receive not only PARP inhibitors, but also tamoxifen or other drugs for positive ESR1 patients as therapeutic drugs." (PMID 40141415, 2025). "Similar to BRCA1 and BRCA2 PV carriers, breast cancers do occur at a young age in women with PJS." (PMID 40317347, 2025). "Triple negative breast cancer (TNBC) was predominantly observed in BRCA1 mutation carriers, while BRCA2 mutation carriers more commonly presented with the luminal phenotype breast cancer or DCIS." (PMID 41083355, 2025). "Combining data from two different breast cancer cohorts (n = 1404 tumours), we labelled HRD status following the same methodology employed by the HRDetect algorithm, which was based on the status of BRCA1/2." (PMID 40260608, 2025). "Adjustment for reproductive factors did not change the estimates, suggesting that these breast cancer risk factors have negligible effects as confounders for the association between BRRM and RR-BSO and breast cancer in BRCA1/2 carriers." (PMID 40974500, 2025). "Chemotherapy receipt is high in BRCA1/2 and PALB2-associated breast cancers including in early stage, node-negative disease." (PMID 40275390, 2025). "Previous studies have shown contradictory findings about breast cancer-specific mortality between BRCA1/2 PV carriers and noncarriers." (PMID 40405286, 2025). "In summary, postmenopausal carriers of PVs in BRCA1/2, ATM, CHEK2, and PALB2 are unlikely to have substantial (twofold or greater) elevations in the risk of developing breast cancer due to reproductive and lifestyle exposures." (PMID 40298171, 2025). "Our study is limited by lack of knowledge as to how the status of P/LP BRCA1 and BRCA2 variants impacted treatment of individual patients with breast cancer or how many patients took advantage of cascade testing." (PMID 40952741, 2025). "A correlation was also reported between PARP1 and BRCA1/2, and at the same time, with ERBB2 and PGR in the luminal B subgroup; such results can indicate that those breast cancer patients can receive Anti-HER2 Monoclonal Antibodies and anti-PGR drugs available in the clinic at present." (PMID 40141415, 2025). "While a positive BRCA1/2 test is highly predictive of breast cancer, a negative test does not rule out breast cancer." (PMID 40500782, 2025). "BRCA1 and BRCA2 carriers without prior breast cancer have the option to undergo risk-reducing mastectomy (RRM)." (PMID 40728683, 2025). "Assess the impact of germline BRCA1/2 (gBRCA1/2) status on anthracyclines-induced cardiotoxicity (AIC) in patients with early breast cancer and no prior anti-HER2 therapy." (PMID 39561108, 2025). "Therefore, the overall prevalence of germline BRCA1 and BRCA2 carriers among Brunei breast cancer patients were 0% and 5%, respectively." (PMID 40531958, 2025).
breast cancer (continued). "This study emphasizes CYP4B1, CYP4F12, and CYP4F3 gene expression levels, presenting tumor versus normal tissue analysis, their expression adjusted by stages, their correlation with BRCA1, BRCA2, and ESR1, the estrogen receptor status, and the overall survival analysis in breast cancer patients." (PMID 40723371, 2025). "PRMT5 regulates BRCA1 mRNA stability by promoting nuclear translocation of ALKBH5, which demethylates BRCA1 transcripts under doxorubicin treatment, thereby enhancing repair capacity and reducing chemotherapy efficacy in breast cancer cells." (PMID 41204384, 2025). "Unlike BRCA1/2 mutation carriers, bilateral breast cancer was not commonly seen in BARD1 mutation carriers, while 29.8% of the BRCA1 and BRCA2 mutation carriers developed bilateral breast cancers (p-value = 0.039)." (PMID 40805222, 2025). "Steroid HR status but not BRCA1/2 status is the strongest predictor of NACT efficacy in breast carcinomas." (PMID 40547808, 2025). "Sensitivity analyses of the association between BRCA1/2 (and PALB2) variants and breast cancer in women without a strong family history yielded consistent estimates." (PMID 38270937, 2024). "We confirmed here that protons are more effective in killing breast cancer cells independent of BRCA1 status." (PMID 39730675, 2024). "A total of 12 patients (14.6%) remained alive with active disease, while 10 patients (12.2%) had succumbed to breast cancer, 6 of whom presented advanced stages (IIIB, n = 4; IIIC, n = 1; IV, n = 1), and most carried PVs in the BRCA1 (n = 4; 40.0%) and BRCA2 (n = 3; 30.0%) genes." (PMID 38893140, 2024). "As to genes other than BRCA1 and PALB2 that may be involved in the anti-proliferative action exerted by ATRA in mammary tumors, important clues come from gene-expression and DNA-methylation studies." (PMID 38360674, 2024). "Finally, our new data show that the amounts of BRCA1 and MGMT mRNA in WBC RNA are much higher in patients with breast cancer and CF epimutation carriers compared to the control group." (PMID 38542081, 2024). "Individuals with a pathogenic variant in BRCA1, BRCA2, or PALB2 had a risk of breast cancer well above 20% at age 70, regardless of their PRS or family history." (PMID 39669587, 2024). "Given the patient’s family history of breast cancer, the patient was tested for BRCA1 and BRCA2 for which the results were negative." (PMID 38910622, 2024). "This study was designed to evaluate the influence of BZA on ERα and BRCA1 in T-47D and MCF-7 breast cancer cell lines, utilizing Western blot analyses, cellular viability assessments, apoptosis assays, and Reverse-Transcription Quantitative Real-Time Polymerase Chain Reaction (RT-qPCR) studies." (PMID 38398090, 2024). "Compared with HRDetect, CHORD requires less preprocessing of the data, was trained on a pan-cancer cohort as opposed to a breast cancer cohort, and includes the ability to predict BRCA1 vs BRCA2 subtypes." (PMID 39485057, 2024). "Oophorectomy has been shown to diminish breast cancer mortality in carriers of BRCA1, BRCA2 and CHEK2 mutation mutations but has not yet been studied in breast cancer patients with ATM mutations." (PMID 39543654, 2024). "In our study, we clearly showed a 1.8% mutation rate of high penetrance genes, with 1.4% from BRCA1 and 0.5% from BRCA2, concealed in non-high-risk breast cancer patients, who needed alternations in management during their ongoing healthcare." (PMID 39272924, 2024). "Second, genetic testing does not capture epigenetic alterations such as BRCA1 promoter methylation, a mechanism of BRCA1 inactivation that is present in approximately 11% of ovarian cancers and 13% to 25% of breast cancers." (PMID 39485057, 2024).
breast cancer (continued). "Pathogenic/likely pathogenic variants in the BRCA1 gene were found more often in patients with ER-negative BC compared to ER-positive BC (10.9% vs. 4.2%, p < 0.001), while P/LP variants in CHEK2 were exclusively identified in BC patients with ER-positive breast cancer (3.4% vs. 0%, p < 0.001)." (PMID 39684352, 2024). "While mammography detects calcifications in BRCA2-related breast cancer, reports indicate a lack of calcifications in BRCA1-related breast cancer." (PMID 39174799, 2024). "BOADICEA V5’s newest version includes the effects of pathogenic variants (PVs), not restricted to BRCA1 and BRCA2 genes but also in PALB2, CHEK2, ATM, and BARD1 for the breast cancer model and RAD51D, RAD51C, and BRIP1 for the ovarian cancer model." (PMID 39590369, 2024). "Even in a single study that included only BRCA1 carriers, those with a history of breast cancer were not eligible to take part." (PMID 39201170, 2024). "BRCA2 significantly positively correlated in T-47D (Pearson r = 0.9366, p<0.0059) breast cancer cells and BRCA1 & p16 negatively correlated but not significant." (PMID 38711004, 2024). "Although several studies have analyzed the oncologic outcomes between BRCA1/2 carriers and non-carriers, the impact on breast cancer patients is still unclear." (PMID 38689097, 2024). "Several genes in breast cancer exhibit CpG island hypermethylation, and in several instances, aberrant activity of DNA methyltransferases led to the hypermethylation and silencing of HOXA5, TMS1, p16, RASSF1A, and BRCA1 genes with tumour suppressor behavior." (PMID 39846533, 2024). "In a large, multicentered cohort study of 548 NSMs performed on 346 BRCA1/2 carriers across nine institutions in the United States, no new breast cancers were diagnosed on the side of the procedure at a median follow-up of 34 months." (PMID 38248108, 2024). "This may be possibly due to the well-known gene- and gender-specific role of BRCA1/2 PVs in the two sexes, with BRCA1 PVs mainly involved in females, while BRCA2 PVs are mainly involved in male breast cancers." (PMID 38339299, 2024). "The probability of not having died due to breast cancer was 99.7% for the RRBM BRCA1 group and 93% for the surveillance group." (PMID 38717180, 2024). "Resveratrol, a phytochemical present in grapes, berries, and peanuts, has been discovered to regulate BRCA1 and BRCA2 genes in breast cancer cells and has inhibitory effect on cellular events associated with tumor initiation, promotion and progression, according to previous research." (PMID 38711004, 2024). "For this reason, HRT should not be carried out after RRSO in premenopausal BRCA1/2-pV carriers or of carriers of pV other breast and/or ovarian cancer genes or genes of the Lynch-syndrome after diagnosis of breast cancer." (PMID 39259360, 2024). "A statistical analysis of BRCA1/2 mutation carriers and non-carriers in Chinese Hakka breast cancer patients revealed that family history, bilateral cancer, HER2-, and Ki67 ≥ 15% were significant independent predictors of BRCA1/2 pathogenic variants." (PMID 38167124, 2024). "To date, no clear association exists between BRCA1/2 mutations and GIST, with only rare reports available, including a patient harboring simultaneous BRCA2 and KIT germline mutations manifesting as breast cancer and multiple GISTs, respectively." (PMID 39199677, 2024). "Women with a BRCA1 mutation and a breast cancer diagnosis have reduced time to progression and survival compared with BRCA2 mutation carriers and noncarriers of BRCA1/2 mutations." (PMID 38817906, 2024). "Normal human physiology includes both BRCA1 and BRCA2, which are breast cancer genes." (PMID 38241592, 2024).